CCND1 (cyclin D1)
Diseases named in the same sentence as CCND1 in open-access papers (continued):
Sharing a sentence is not in itself a finding about the gene and the disease.
cancer (continued). "There are many connections between Wnt and PI3K/AKT signaling pathways, including common components relevant to cancer development such as MYC, GSK3, PTEN, and CCND1." (PMID 37856394, 2023). "LOXL2 associates with and catalyses H3K36ac deacetylation thus blocking H3K36ac-dependent transcription of genes, including MYC proto-oncogene, BHLH transcription factor (MYC), cyclin D1 (CCND1), HIF1A, and CD44, thereby restricting cancer cell proliferation." (PMID 37762708, 2023). "CXCR2 activation also reduces the expression of p21 and increases the expression of cyclins and cyclin dependent kinases such as cyclin A, cyclin B1, cyclin D1, cyclin E, CDK2, and CDK6, thereby promoting the increased proliferation of cancer cells." (PMID 37686093, 2023). "Next, we identified significantly enriched KEGG (Pathways in cancer and PI3K/Akt signaling pathway) and GO (GO:0000122, GO:0045944 and GO:0045893) terms, and identified eight genes (EDN1, CCND1, MYB, MYC, RUNX1, ITGA6, IL6 and FGF2." (PMID 36978140, 2023). "A number of pivotal cancer-related genes, including HER2, CCND1, PIK3CA, and CDKN2A, were pinpointed within the top 500 genes in both the differential signaling network and the analysis of differentially expressed genes." (PMID 38087279, 2023). "In terms of therapeutic strategies, research has shown that correcting CCND1 splicing through antisense oligonucleotides (ASO) and small molecule modulators can be effective in cancer therapy." (PMID 37664052, 2023). "Knockdown of CMTR1 inhibited cancer cell growth both in vitro and in vivo, with a concomitant reduction in the expression of cell cycle-related genes, such as CDKN1A, CDK6, and CCND1." (PMID 37024465, 2023). "Upon estrogen stimulation, ATAD2 is selectively recruited to the promoters of ERα target genes, such as cyclin D1, c-Myc and E2F1, which are required for estrogen-induced cancer cell proliferation." (PMID 36632213, 2023). "Cyclin-D1 expression and average intensity of MAA (MAAavg) were higher in cancer cohort as compared to LRL/HGD (p<0.05)." (PMID 37747904, 2023). "CCND1 is a downstream effector in the Wnt2/β-catenin pathway and activates the cyclin-dependent kinases (CDKs) CDK4 and CDK6 to promote cancer proliferation." (PMID 37056769, 2023). "Reduction in DVL2 function via shRNA resulted in reduced mRNA expression of CCND1 and VEGFA, genes which are involved in cancer cell proliferation and angiogenesis respectively in both SKBR3 and BT474 cells (p < 0.05)." (PMID 36809986, 2023). "Most hematological malignancies are characterized by overexpression of certain cancer promoting genes, such as MYC, MCL1 and cyclin D1." (PMID 37552223, 2023). "let-7, the first miRNA discovered in humans, involves in many cancer-related genes such as c-MYC, HMGA2, and CCND1." (PMID 37689710, 2023). "Some of them are involved in the maintenance of cancer stem cells (CSCs), such as MYC (Myc proto-oncogene protein), CCND1 (CyclinD1) and ABCB1 (ABC multidrug transporter)." (PMID 37237497, 2023). "For GP5, CDK12 inactivation and gains of AKT1, GSK3B, PIK3CA, CCND1, and MDM2 were identified as the top truncal druggable targets that would be most likely to obtain a durable response due to their presence in all cancer cells." (PMID 37828555, 2023). "Results revealed a significant up-regulation of MCL1 and CCND1, and a significant down-regulation of IGF1R and PTEN in KIRC patients with varying cancer stages, races, genders, and age groups compared to normal controls." (PMID 37744271, 2023).
cancer (continued). "We used the expression of cyclin D1 and p-AKT (s473), as these pathways are upregulated in cancers and promote oncogenic growth." (PMID 37508547, 2023). "CCND1, known as a proto-oncogene, switches to proximal APA sites in cancer cells and acts as the G1-S phase of the cell cycle regulator." (PMID 37671046, 2023). "Two key players of the cell cycle, CDK6 and CCND1, were connected to palbociclib, the first CDK4/6 inhibitor approved for cancer therapy." (PMID 37359725, 2023). "The IL-6/STAT3 signaling pathway upregulates factors involved in cancer cell proliferation (MYC, cyclin D1), angiogenesis (VEGFA, PDGF), and apoptosis (Bcl-XL)." (PMID 36720310, 2023). "Here, we have found the expression of CCND1 was obviously decreased in METTL3-deleted cells, and the same result was also demonstrated in YTHDF1-silenced cancer cells." (PMID 38001065, 2023). "The expression cor-relationships between METTL3 and its targets, including JAK1, VEGFA, CCND1, and STAT3, was positive in almost all analyzed cancer types." (PMID 38001065, 2023). "Correction of CCND1 splicing by ASO and small molecule modulators has been shown efficacy in cancer therapy." (PMID 37024471, 2023). "In many cancer cell lines, the decrease in hTERT (human TERT) expression is related to the significant down-regulation of CCND1, and the high expression of hTERT significantly up-regulates the expression of CCND1." (PMID 36770809, 2023). "Because the ERK1/2 pathway (consisting of kinases RAS, RAF and ERK1/2) is known to activate the expression of CCND1, and the hyperactivation of ERK1/2 drives cancer cell growth in various cancers." (PMID 37085908, 2023). "We therefore evaluated the expression of a panel of epithelial (KRT5, 7, 8, 18, and CDH1), mesenchymal (VIM, FN1, SNAI1, TWIST1, COL1A1, and PRRX1), and cancer stem cell (ALDH1A2, ALDH7A1, CD44, and CCND1) markers in all samples." (PMID 36980717, 2023). "The findings presented here confirmed that the inhibition of cyclin D1 and survivin by PNU-74654 reduced cancer cell growth." (PMID 37763649, 2023). "In cancer cells derived from hepatocytes (HepG2 and HuH7) and breast epithelia (MCF 7), cyclin D1 depletion increased glucose uptake." (PMID 38152849, 2023). "As above reported, NF-kB plays an important role in HR-HPV induced cancer, since this pathway also leads to cyclin D1 and c-MYC transcription, which in turn also plays an important role in cancer progression." (PMID 37108333, 2023). "Cyclin D1 is frequently deregulated in PTC and serves as a biomarker of cancer phenotype and disease progression." (PMID 37427143, 2023). "As a result, expressions of two target genes of β-catenin, namely CCND1 and MYC, which are important for cancer proliferation, were suppressed." (PMID 36336731, 2022). "Cyclin D1, a mitotic sensor and allosteric activator of CDK4/6, is one of the most common cell cycle regulators in cancer and is often overexpressed in cancer." (PMID 36379920, 2022). "A recent study showed that berberine treatment suppresses cancer cell growth by regulating miR-22 and SP1, which are downstream targets of CCND1 and BCL2 in HCC." (PMID 35723348, 2022). "Of note, a decrease in nuclear β-catenin in the Wi-ACAPE treated cells was associated with a decrease in Wnt/β-catenin regulated genes (c-Myc, Cyclin D1 and AXIN) critically involved in cancer metastasis." (PMID 35159054, 2022).
cancer (continued). "Cyclin D1 and CDK4 were found to mediate therapeutic resistance to HER2 blockade in HER2-positive cancers." (PMID 36387174, 2022). "The enhancement of cyclin D1 expression and cyclin-dependent kinase activation in SEMA6C-low cancer created a druggable target of CDK4/6 inhibitors." (PMID 35269749, 2022). "In CRC cells, IL-6 induced Cyclin D1 expression, and in 3D CRC spheroids stimulated the expansion of cancer stem cells." (PMID 35625868, 2022). "Previous research has described the role of cyclin D1 and CDK4 in augmented cell proliferation and poor prognosis in some types of cancer." (PMID 35448172, 2022). "Well-characterized target genes have been described, including those belonging to the HES and HEY gene family, CCND1 and MYC, influencing cancer cell proliferation." (PMID 35682974, 2022). "The seed gene CCND1 in MCODE networks of DEGs has been shown to interact with tumor suppressor protein Rb, and seems to be a pan-cancer actor." (PMID 35244719, 2022). "During cell cycle progression, cyclin D1 and CDK2 are critical cell cycle regulators involved in the G0/G1 to S phase transition and serve as theraputic targets in several types of cancers, including NSCLC." (PMID 35235599, 2022). "Thus, decreasing cyclin D1 by degradation could be a promising target strategy for cancer therapy." (PMID 36059670, 2022). "As a result, it was Cyclin D1 and CDK4 expression levels were downregulated during the G0/G1 arrestment in the cancer cells." (PMID 36263164, 2022). "Treatment with 100 mg/kg corylin in the AOM/DSS mice led to significantly decreased cancer stem cell and intestinal epithelial cell proliferation, including LGR5, CD44, Ki67, PCNA, BrdU, and Cyclin D1 levels, compared with the AOM/DSS group." (PMID 35269806, 2022). "CCND1 and MYC are two typical target genes of β-catenin and these genes play an important role in cancer proliferation." (PMID 36336731, 2022). "ATAD2 is directly associated with estrogen-bound ERα and ACTR, and thus elevates the expression of ERα-targeted cell cycle regulators, such as cyclin D1, Myc, and E2F1, which promote cancer cell proliferation." (PMID 36139505, 2022). "Immunohistochemical methods showed that cyclin D1 was expressed in ESCC tissue and normal esophageal mucosa adjacent to cancer." (PMID 35242498, 2022). "The MCODE analysis identified gene clusters for each cancer type with MYC, PCNA, PARP1, IDH1, FGF10, PTEN, and CCND1 as hub genes with high connectivity." (PMID 35001007, 2022). "Potential targets of statins for cancer treatment identified by LIGHTHOUSE included STAT3, CCND1, AKT1, and CCL2." (PMID 36246574, 2022). "In particular, PPRHs interfering with promoter activation (HpMYC-G4-PR-C) and transcription (HpMYC-I1-T) dose- and time-dependently regulated these cancer cells and decreased MYC and downstream Cyclin D1 expression at concentrations as low as 25 nM." (PMID 36613820, 2022). "The expression of cyclin D1 and miR-195 in paired GBM and non-cancer tissues from GBM patients was also detected by performing RT-qPCR." (PMID 35287551, 2022). "Alpha-Toc induced cell cycle arrest in cancer cells through the inhibition of protein kinase C (PKC) and reduced cyclin D1 and cyclin E levels." (PMID 35889829, 2022). "Frequent copy‐number aberrations were also found for important cancer genes, such as CDKN2A, KIT, MDM2, CCND1, CDK4, and PAK1, among others." (PMID 35229492, 2022). "In the present study, we discovered that RASAL2, a RAS-GTPase-activating protein, acted as an oncogene to regulate cancer cell proliferation and the cell cycle and contributed to tumorigenesis via the PI3K/AKT/cyclin D1 pathway." (PMID 35668070, 2022).
cancer (continued). "The expression of CCND1 and CDK4/6, which are well-acknowledged regulator not only in cell cycle but also in cancer progression, was also found to be downregulated upon CDCA8 knockdown 37-39." (PMID 35517403, 2022). "According to reports, Myr inhibits the proliferation of various cancer cells through multiple signaling pathways, including PI3K/AKT, PAK1/MEK/ERK1/2, cyclin D1/PCNA, STAT3 and so on." (PMID 35646711, 2022). "GLI1 promotes cell proliferation by inducing cyclin D1 expression, while GLI2 is known to increase cancer cell proliferation, tumorigenicity, and metastatic potential." (PMID 35047127, 2022). "Cyclin D1, with its partner CDK4/6, plays a dominant role in regulating G1/S cell cycle progression of various cancer cells." (PMID 35078428, 2022). "The upregulation of ZBTB10 and ZBTB4 expression inhibited SP transcription factors and, as a result, the expression of several downstream target genes such as EGFR, c-MET, cyclin D1, and NFB, resulting in cancer cell growth inhibition and apoptosis induction." (PMID 35530318, 2022). "The expression of cyclin D1 and MMP-11 decreased, the cycle of cancer cells was blocked, and the metastatic ability of cancer cells was inhibited." (PMID 36034798, 2022). "They inhibited the proliferation and metastasis of cancer cells by downregulating the PI3K/AkT signaling cascade and reducing cyclin D1 levels via the activation of GSK-3β." (PMID 35807651, 2022). "In DU145 cells, TUBB4A KO or MYH9 KD increased the expression of GSK3β but decreased the expression of nuclear β-catenin and its downstream targets, cyclin D1 and c-MYC, suggesting TUBB4A/MYH9-mediated GSK3β/β-catenin signaling in human cancer cells." (PMID 35589707, 2022). "STAT3’s target genes are mainly implicated in processes of cell differentiation, such as survivin (BIRC5), B-cell lymphoma (Bcl)-2, cyclin D1, c-Myc or vascular endothelial growth factor (VEGF), thus their expression plays a key role in cancer promotion." (PMID 36185259, 2022). "In IOT, the LINC00324/miR-214-5p/CDK6|CCND1|MDM2|MDM4 axis promotes cancer cell proliferation and inhibits cancer cell apoptosis." (PMID 36620587, 2022). "We observed that the expression of 26 cancer driver genes is downregulated by fb-PMT, representative examples of which include EGFR, NOTCH1/2, MAPK1, CCND1, and BRAF." (PMID 36879662, 2022). "The whole-exome sequencing of osimertinib-resistant patient-derived cancer cell lines revealed amplification of GLI1, CDK4, and CCND1." (PMID 35584089, 2022). "Cyclin D1 is one of CREB/ATF1 and wnt/β-catenin targets and a critical driver of cancer cell proliferation." (PMID 33917483, 2021). "Snail and Twist are the hallmarks oncogenic transcription factors that downregulate the expression of epithelial marker E-cadherin and upregulate EMT markers fibronectin, c-Myc, cyclin D1, MMP2, and MMP9 in various cancers." (PMID 34711805, 2021). "We observed that BRCA1/2 gene alterations were mutually exclusive with amplification of all the oncogenes examined in the breast (CCND1, CCNE1 and CDC6) and ovarian (CCND1, CCNE1 and BRAF) cancer cohorts." (PMID 34389725, 2021). "Using bioinformatics, we successfully identified CCND1/CDK4/PLK1/CD44 as oncogenic signatures, which drives cancer progression and resistance to treatment, and as potential druggable candidates for both NSC7565600 and NSC765691 small molecules." (PMID 34063946, 2021). "CyclinD1 (CCND1), a prime amplified gene in various cancers, was also reported to participate in angiogenesis by repressing the proliferation of endothelial cells." (PMID 34899707, 2021).
cancer (continued). "Meanwhile, the inhibition of FOXM1 repressed the expression of CDK6, CCND1, CDK2, CCNE2, E2F2, and CDC25A to arrest the cell cycle at G2 phase, which blocks the promotion of cancer-cell mitosis." (PMID 34880209, 2021). "The most dysregulated genes were related with the signaling pathways such as AKT-MTOR, CYCLIN D1, KRAS, EIF4E, RB, and ATM, which play an essential role in cancer cell proliferation, survival, and response to external stimuli." (PMID 34944712, 2021). "Treatment of RTK-driven cancer cell lines with zotatifin for 24 h resulted in dose dependent downregulation of HER2, FGFR1 and FGFR2 protein levels, as well as cyclin D1 (a zotatifin target gene)." (PMID 34900714, 2021). "Herein, we used NGS to interrogate the complex genomic landscape of 2457 patients with diverse cancers, of whom 507 patients harbored specific, potentially sensitizing G1/S phase cell-cycle (CDK4/6, CCND1/2/3, or CDKN2A/B) gene alterations." (PMID 33427211, 2021). "For instance, tissue microarrays identified that LIN28A expression was increased in epithelial tumors and promoted cell cycle progression by regulating CDK2, CCND1, and CDC25A in cancer cells." (PMID 34868981, 2021). "The differentiation ability of the human cancer cells A549 is decreased by β-sitosterol, which also induces G0/G1 cell cycle arrest, decreased CDK4 and cyclin D1 levels, and increased expression of p21/Cip1 and p27/Kip1." (PMID 34679718, 2021). "Western blotting showed that the expression of cyclin B1 and cyclin D1 was decreased by the downregulation of EIF3G, suggesting that the cell cycle and mitotic events are controlled by EIF3G in cancer cells." (PMID 34202873, 2021). "KDM4B and MLL2 synergistically regulate cancer cell proliferation through their target genes, including myeloblastosis (MYB), myelocytomatosis (MYC), and cyclin D1 (CCND1)." (PMID 34359832, 2021). "First, proteins related to the cell cycle, such as cyclin D1, cyclin E, and CDK4, can promote cell proliferation in normal and cancer cells." (PMID 33722298, 2021). "Cyclin D1 (CCND1) is one of the cell cycle regulators modulating the occurrence and development of malignant tumors, which is typified by overexpression." (PMID 34806539, 2021). "MYC and CCND1 are well-known targets of YAP, and their contribution to cell proliferation, cell cycle, and cancer progression is well-established." (PMID 33514403, 2021). "IL‐6/STAT3 signalling upregulates the expression of genes involved with cell proliferation (c‐Myc and cyclin D1), angiogenesis (VEGF) and the inhibition of apoptosis (Bcl‐xL and survivin) in cancers." (PMID 33382511, 2021). "Except for genes that had been shown to be mis-regulated in many cancer types, such as CDKN2A, CCND1, and IL6, we also detected a cohort of genes that had been newly or rarely reported in LC." (PMID 33628593, 2021). "TRIM8 overexpression downregulated the protein expressions of Wnt5a, β-Catenin, c-Myc and Cyclin D1, and upregulated the protein expression of active Caspase-3 in LV-TRIM8 cancers." (PMID 33858426, 2021). "Because STAT3 regulates genes that promote cancer cell survival, proliferation, and invasion, we next tested mRNA expression changes of previously established STAT3 target genes, BCL2L1, BIRC5, CCND1, and MMP9 after short-term Olaparib exposure." (PMID 34956861, 2021). "Among the 11q13-amplified cancer samples that carry amplification of SHANK2 and/or Cyclin D1, 233 amplified both SHANK2 and Cyclin D1, 412 amplified only SHANK2 and 50 amplified only Cyclin D1." (PMID 32661924, 2021).